CMYA5 (cardiomyopathy associated 5)
Description:
May serve as an anchoring protein that mediates the subcellular compartmentation of protein kinase A (PKA) via binding to PRKAR2A (By similarity). May function as a repressor of calcineurin-mediated transcriptional activity. May attenuate calcineurin ability to induce slow-fiber gene program in muscle and may negatively modulate skeletal muscle regeneration (By similarity). Plays a role in the assembly of ryanodine receptor (RYR2) clusters in striated muscle (By similarity).
Synonyms: C5orf10; SPRYD2; TRIM76; DKFZp451G223
Tractability: No criterion of Open Targets' tractability assessment is met for any kind of drug.
Gene: Protein-coding gene on chromosome 5 (79,689,777 to 79,800,607, forward strand). Ensembl gene ENSG00000164309.
Subcellular location: Nucleus; Sarcoplasmic reticulum; Cytoplasm; Cytoplasm, perinuclear region; Cytoplasm, myofibril, sarcomere, M line
Subcellular location (Human Protein Atlas): Endoplasmic reticulum; Plasma membrane
Gene Ontology:
Cellular component: cytoplasm; nucleus; perinuclear region of cytoplasm; sarcoplasmic reticulum; M band
Genetic constraint (gnomAD): Loss-of-function variants: 225 observed, 311.35 expected, observed/expected ratio (o/e) 0.72, 90% interval 0.65 to 0.81. The upper end of that interval is the gene's LOEUF score, 0.81, which puts it in group 3 of 6, group 1 being the genes least tolerant of losing a copy. Missense variants: 4,439 observed, 4,766.1 expected, observed/expected ratio (o/e) 0.93, 90% interval 0.91 to 0.95. Synonymous variants: 1,588 observed, 1,768.3 expected, observed/expected ratio (o/e) 0.9, 90% interval 0.86 to 0.94.
Homologues: Orthologues: chimpanzee CMYA5 (97% identical), macaque CMYA5 (90% identical), pig CMYA5 (71% identical), dog CMYA5 (69% identical), guinea pig CMYA5 (59% identical), rat Cmya5 (56% identical), rabbit CMYA5 (54% identical), mouse Cmya5 (54% identical), zebrafish cmya5 (12% identical), zebrafish si:ch1073-398f15.1 (5% identical). Paralogues in human: FSD2 (6% identical), FSD1L (3% identical), FSD1 (3% identical).
Diseases named in the same sentence as CMYA5 in open-access papers:
CMYA5 is named in the same sentence as 22 diseases in open-access papers, as found by Europe PMC text mining. Sharing a sentence is not in itself a finding about the gene and the disease. The quoted sentences say what the papers report.
cardiomyopathy (6 papers, 2015 to 2025). A disease of the heart muscle or myocardium proper. "Although CMYA5 was named a “cardiomyopathy associated” gene, a search showed that the OMIM database did not map the locus of myospryn to a susceptibility region for cardiovascular disease." (PMID 26573135, 2015). "The cardiomyopathy associated gene CMYA5 (myospryn) that binds to the C-terminus of titin was also shown to interact with PKA, however, currently it is not well understood, which role PKA exactly plays in the response to mechanical and humoral stress in the M-band." (PMID 30738787, 2020). "It is tempting to speculate that differential expression of CMYA5 in cardiomyopathies and muscular dystrophy may contribute to the disease process through physical interactions with RyRs that affect their clustering or association with other proteins in the couplon." (PMID 28740084, 2017).
schizophrenia (3 papers, 2015 to 2021). A major psychotic disorder characterized by abnormalities in the perception or expression of reality. "CMYA5 has been associated with schizophrenia, depression and BD.CMYA5 interacts with dysbindin, which has been linked to both schizophrenia and BD." (PMID 26190982, 2015). "Cmya5 is an expression biomarker for a number of diseases affecting striated muscle and may also be a schizophrenia risk gene." (PMID 28740084, 2017).
breast carcinoma (2 papers, 2020 to 2021). "ASPM and CMYA5 are predicted as novel oncogenes in breast cancer, while ERBB2 is an already well-known oncogene in breast cancer." (PMID 31900418, 2020).
left ventricular hypertrophy (2 papers, 2019). Enlargement of the LEFT VENTRICLE of the heart. "The overexpression of CMYA5 is associated with left ventricular hypertrophy." (PMID 30925936, 2019).
Anxiety (1 paper, 2015). Intense feelings of nervousness, tension, or panic often arise in response to interpersonal stresses. "We identify four genes (TNR, RXRG, MCTP1, and CMYA5) associated with anxiety in mice and risk of BD in humans." (PMID 26190982, 2015). "CMYA5, MCTP1, RXRG, and TNR are associated with mouse anxiety and human BD." (PMID 26190982, 2015). "Further, we found that Cmya5 expression correlates with anxiety-like and depression-like behavior." (PMID 26190982, 2015). "Finally, when we correlate striatal expression of all four of our candidate genes against the large BXD phenotype dataset, we find that Tnr, Rxrg, and Mctp1 expression correlates with dopamine related traits, whereas Cmya5 expression correlates with anxiety- and depression-like traits." (PMID 26190982, 2015).
bipolar disorder (1 paper, 2015). A disorder of the brain that causes unusual shifts in mood, energy, activity levels and the ability to carry out day-to-day tasks. "Overall, our study provides evidence for the association of CMYA5, MCTP1, RXRG, and TNR with bipolar disorder." (PMID 26190982, 2015). "We then investigate the homologous genomic regions in human bipolar disorder GWAS data and thus identify four candidate genes (TNR, RXRG, MCTP1, and CMYA5)." (PMID 26190982, 2015).
centronuclear myopathy (1 paper, 2023). Centronuclear myopathy (CNM) is an inherited neuromuscular disorder characterized by clinical features of a congenital myopathy and centrally placed nuclei on muscle biopsy. "This study suggests that Spegα and Spegβ display functional redundancy, identifies Esd, Cmya5 and Fsd2 as components of both cardiac dyads and skeletal muscle triads and lays the groundwork for the identification of new therapeutic targets for centronuclear myopathy." (PMID 37709832, 2023).
endometrial cancer (1 paper, 2021). Primary or metastatic malignant neoplasm involving the endometrium (mucous membrane that lines the endometrial cavity). "Prior studies have reported that the difference in CMYA5 expression levels were detected as a potential driven gene in Taiwanese patients with endometrial cancer." (PMID 35111661, 2021).
glioma (1 paper, 2021). A benign or malignant brain and spinal cord tumor that arises from glial cells (astrocytes, oligodendrocytes, ependymal cells). "In contrast to STEAP3, the roles of ARL9 and CMYA5 in glioma have rarely been reported and remain obscure." (PMID 35111661, 2021).
liver cancer (1 paper, 2021). An epithelial or non-epithelial malignant neoplasm that arises from the liver. "For lung cancer, GMPS, EPHA10, C10orf54, and MAGEA6 are highly expressed in different subtypes; for liver cancer, CMYA5, DEPDC6, FAU, VPS24, RCBTB2, LOC100133469, and SLC35B4 are significantly expressed in different subtypes." (PMID 33747053, 2021).
metabolic syndrome (1 paper, 2019). A cluster of metabolic risk factors for CARDIOVASCULAR DISEASES and TYPE 2 DIABETES MELLITUS. "Seven genes (WDR27, GNAS, DOK7, EDN3, MCF2L, PRKG1, and CMYA5) were selected based on genomic location and relevance to metabolic syndrome." (PMID 31170227, 2019). "We investigated the correlation of DNA methylation with expression of seven genes (WDR27, GNAS, DOK7, EDN3, CMYA5, PRKG1, and MCF2L) selected on the basis of their known functions in metabolic syndrome, and their locations in functional genomic regions." (PMID 31170227, 2019).
Obesity (1 paper, 2014). Accumulation of substantial excess body fat. "The eSNP sources reside in genes CMYA5 and RPL27A which are obesity GWAS loci." (PMID 25210734, 2014).
cancer (2 papers, 2021 to 2025). A tumor composed of atypical neoplastic, often pleomorphic cells that invade other tissues. "MUC16 has been implicated in modulating cell adhesion, immune evasion, and chemoresistance in other cancers, while CMYA5 is involved in cytoskeletal organization and could affect cell motility." (PMID 41037214, 2025). "We also detected differentially methylated regions in cancer-related genes, such as CMYA5, TSLP, ZNF503, and ZNF217, which suggest that the methylation status of these genes may be involved in tumorigenesis or cancer progression." (PMID 34527193, 2021).
psychiatric disorder (2 papers, 2015 to 2021). A disorder characterized by behavioral and/or psychological abnormalities, often accompanied by physical symptoms. "Among the 36 duplicated genes, CMYA5, HOMER1, SERINC5 and RasGRF2 genes have been repeatedly associated with SCZ and other psychiatric disorders." (PMID 34946848, 2021).
tumor (2 papers, 2025). "The results showed that IGF2BP2, PLAU, and CEP55 were found to be statistically significantly higher expressed in tumours than in normal samples, while CMYA5 was statistically significantly lower expressed in tumours." (PMID 40762677, 2025).
CMYA5 also shares sentences with these, for which no sentence is quoted: cardiac hypertrophy (2 papers); depression (1); hypertrophic cardiomyopathy (1); hypertrophy (1); lung carcinoma (1); mental disorder (1); muscular dystrophy (1).